S1PR2 (sphingosine-1-phosphate receptor 2)
Diseases named in the same sentence as S1PR2 in open-access papers (continued):
Sharing a sentence is not in itself a finding about the gene and the disease.
deafness (7 papers, 2016 to 2023). An inherited or acquired condition characterized by the complete loss of the ability to hear from one or both ears. "Knocking out S1PR2 causes hair cell degeneration and deafness in mice." (PMID 30563056, 2018). "There were no instances of multiple variants being identified in the same gene, and only one was in a known deafness gene, S1PR2." (PMID 37163093, 2023). "There were no instances of multiple variants being identified in the same gene, and only two were in known deafness genes, S1PR2 and PIEZO1." (PMID 38011198, 2023).
hearing loss (7 papers, 2016 to 2023). "S1PR2 is important for cell migration and S1PR2 mutations induce hearing loss by disrupting endocochlear potential gradients." (PMID 30563056, 2018). "Discussion and research on developing treatments for hearing loss often focus on sensory hair cells, but our report provides the first clear example of the involvement of S1PR2 in EP generation and the need to restore EP if treatments are to be successful." (PMID 27383011, 2016). "The new mouse mutant we report here provides mechanistic insight into the pathological processes underlying S1PR2-related hearing loss." (PMID 27383011, 2016). "Finally, we investigated the potential involvement of S1PR2 in human hearing loss by asking if variants in this gene show association with auditory thresholds in the 1958 British Birth Cohort31." (PMID 27383011, 2016). "Most importantly, 27 GPCRs were found to be associated with hearing loss, 5 of which were directly associated with human hearing disorders (VLGR1, mGluR7, V2R, EDNRB, and S1PR2)." (PMID 36311029, 2022).
injury (7 papers, 2015 to 2025). Damage inflicted on the body as the direct or indirect result of an external force, with or without disruption of structural continuity. "We hypothesize that Ks extracts may exert protective effects against APAP-induced acute liver injury by modulating the SPHK1/S1P/S1PR2/S1PR4 pathway and the Nrf2/Keap1 pathway, thereby mediating oxidative stress and inflammatory responses." (PMID 40811614, 2025). "We have previously reported that TCA-induced activation of S1PR2 promotes cholestatic liver injury." (PMID 36224648, 2022). "Second, we analyzed whether targeting macrophage S1PR2 may influence NLRP3 inflammasome priming and activation in cholestatic liver injury." (PMID 32695095, 2020). "To investigate the potential role of S1PR2 and S1PR3 in BMM migration during cholestatic liver injury, we performed an EGPF-positive BM cell transplantation experiment followed by BDL-induced liver injury with the administration of JTE-013 or CAY-10444." (PMID 26324256, 2015).
myocardial infarction (7 papers, 2018 to 2025). Gross necrosis of the myocardium, as a result of interruption of the blood supply to the area, as in coronary thrombosis. "The myocardial infarct size as a percentage of the area at risk was significantly smaller in the S1PR2 agonist group (14.2% ± 1.9%, n = 8) than in the Vehicle group (32.1% ± 5.5%, n = 8, p < 0.001)." (PMID 40245180, 2025). "Study limitations are that it is unclear whether the protective effects of the S1PR2 agonist, SID46371153, in rabbit myocardial infarction are solely attributable to S1PR2 in Muse cells." (PMID 40245180, 2025). "Acute myocardial infarction (AMI) model rabbits were subcutaneously injected either with Vehicle (n = 15), S1PR2‐agonist (n = 16), or S1PR2‐agonist + S1PR2‐antagonist (n = 10)." (PMID 40245180, 2025). "Furthermore, in a murine myocardial infarction (MI), S1P can enhance its efficacy in stimulating angiogenesis through the S1PR2/ERK1/2-MMP-9 pathway." (PMID 38250717, 2024). "In a study using a myocardial infarction rabbit model, S1PR2 expression was higher in Muse cells than in non-Muse cells." (PMID 35862404, 2022). "The importance of the S1P-S1PR2 axis in Muse cells was confirmed by S1PR2 knockdown with small interference RNA in Muse cells and by co-administration of the S1PR2-specific antagonist JTE-013 in a rabbit acute myocardial infarction model." (PMID 36339573, 2022).
neuroblastoma (7 papers, 2016 to 2023). Neuroblastoma (NB) is the most common solid, extracranial childhood tumor. "Interestingly, similar findings have been reported in neuroblastoma cells, which also exhibited enhanced formation of S1P that ligated S1PR2 to induce VEGF expression." (PMID 26884643, 2016).
B-cell lymphomas (6 papers, 2016 to 2025). "It is believed that S1PR2 promotes confinement of B cells within the follicle center since loss of S1PR2 expression in S1PR2-/- mice is associated with loss of germinal center confinement, abnormal growth of B cells and development of B-cell lymphomas." (PMID 35756630, 2022). "The composite HL and FL in case 4 shared six mutations, one of them being a nonsense mutation in S1PR2 (25% VAF in FL, 19% VAF in HL), a tumor suppressor gene commonly silenced in aggressive B-cell lymphomas." (PMID 40404986, 2025).
diabetes (6 papers, 2016 to 2024). "Conversely, induction of S1PR2 has been related to diabetes whereas expression of S1PR3 was unchanged." (PMID 32033121, 2020). "Targeting S1P modulation or inhibiting S1PR2 may provide therapeutic advantages for diabetes and safeguard against retinal neurodegeneration." (PMID 39777222, 2024). "However, the role of S1PR2 in diabetes-induced glomerular endothelial cell dysfunction remains unclear." (PMID 30999892, 2019).
endothelial dysfunction (6 papers, 2015 to 2025). In vascular diseases, endothelial dysfunction is a systemic pathological state of the endothelium (the inner lining of blood vessels) and can be broadly defined as an imbalance between vasodilating and vasoconstricting substances produced by (or acting on) the endothelium. "Our results demonstrated that the S1PR2 antagonist (JTE-013) almost completely blocked endothelial dysfunction and associated fission and dysfunction of mitochondria under HG conditions along with down-regulated HG-promoted expression of RhoA/ROCK1." (PMID 30999892, 2019). "S1PR2, which is described as a pro-inflammatory receptor, promotes the endothelial dysfunction in several pathological conditions." (PMID 32033121, 2020). "In PE endothelial cells, the increased expression of Nogo-B, SPPase, and S1P lyase, together with the decreased S1PR1 expression and concomitant S1PR2 upregulation, indicate the onset of an endothelial dysfunction, typical of this disorder." (PMID 32033121, 2020). "Overall, our study provides the first evidence that S1PR2 exerts multiple effects on the fission and dysfunction of mitochondria induced by HG in HRGECs, which in turn contribute to endothelial dysfunction." (PMID 30999892, 2019). "S1P may also instigate endothelial dysfunction through S1PR2 signalling." (PMID 39408263, 2024). "However, the role of S1PR2 activity in the morphology and function of mitochondria of HRGECs and the downstream signaling molecules of S1PR2 coupling associated with mitochondrial and endothelial dysfunctions have not been identified." (PMID 30999892, 2019). "Additionally, the permeability, apoptosis, and migration of cells were determined to evaluate the effects of S1PR2 and ROCK1 inhibition on high glucose-induced endothelial dysfunction." (PMID 30999892, 2019). "That endothelial cell S1PR2 expression alone is upregulated in a hyperglycaemic environment whilst other S1PR expression is reduced may suggest that S1P is a key signalling intermediate linking diabetes and metabolic dysfunction with endothelial dysfunction." (PMID 39408263, 2024). "S1P interacting with S1PR2 may also have a pro-atherosclerotic effect by promoting the inflammatory response of endothelial cells due to the increased expression of pro-inflammatory factors such as tumor necrosis factor α (TNF-α), interleukin 1 (IL-1), stimulating endothelial dysfunction." (PMID 36119733, 2022).
Hepatic steatosis (6 papers, 2019 to 2025). Steatosis is a term used to denote lipid accumulation within hepatocytes. "Another study found that blocking S1PR2 enhanced liver steatosis and HCC development in a melanocortin-4 receptor-deficient murine model of NASH." (PMID 34440841, 2021). "In this study, we established the role of hepatic S1PR2 signaling in chronic glucocorticoid exposure-induced hypertriglyceridemia and hepatic steatosis." (PMID 40490140, 2025). "Our results reveal the possibility that S1PR2 knockdown can alleviate inflammatory response during fatty liver disease via reducing NET formation." (PMID 32424179, 2020). "The S1PR2/3 blockade works as an anti-inflammatory treatment and ameliorates liver inflammation, injury, and fibrosis in fatty liver injury." (PMID 31546702, 2019). "Deletion of either S1PR2 or SphK2 significantly increased hepatic steatosis and inflammation." (PMID 40057751, 2025). "In summary, we identified the important role of S1PR2/3 in fatty liver injury and demonstrated that S1PR2/3 blockade inhibits liver injury in vivo, strongly suggesting S1PR2/3 might serve as therapeutic targets for fatty liver injury." (PMID 31546702, 2019). "S1P is suspected to increase lipid accumulation by activating S1PR2 and S1PR316, and knocking out Sphk1 protected from hepatic steatosis under a high-fat-high-glucose diet." (PMID 37953311, 2023). "Thus, Sphk2 does not play a role in chronic Dex-induced lipid disorders and S1PR2’s role in mediating chronic Dex-induced hypertriglyceridemia and hepatic steatosis likely does not require Sphk2." (PMID 40490140, 2025). "Downstream of S1PR2 activation is the induction of sphingosine kinase 2 (SPHK2) that can translocate to the nucleus to modulate gene synthesis, and in the same study above, the authors found that Sphk2−/− mice at 20 weeks of age spontaneously develop hepatic steatosis." (PMID 34440841, 2021). "Furthermore, S1PR2 knockdown ameliorates liver inflammation and fibrosis by inhibiting NET formation in vivo, which may represent an effective therapeutic strategy for fatty liver diseases." (PMID 32424179, 2020).
osteoporosis (6 papers, 2017 to 2025). A condition of reduced bone mass, with decreased cortical thickness and a decrease in the number and size of the trabeculae of cancellous bone (but normal chemical composition), resulting in increased fracture incidence. "In addition, S1P regulation via SPL inhibition has been demonstrated to enhance bone mass and strength in a S1PR2-dependant manner in vivo, which also effectively ameliorating osteoporosis in S1PR2-deficient mice, suggesting S1P is a potential therapeutic target for bone diseases." (PMID 31293578, 2019). "A previous study in mice showed that pharmacological inhibition of S1PR2 by JTE013 suppressed RANKL-induced osteoporosis." (PMID 33922596, 2021). "For instance, S1PR3 agonists have been shown to enhance bone formation by promoting osteoblast differentiation, whereas S1PR2 antagonists may suppress bone resorption, offering targeted strategies for osteoporosis management." (PMID 41367909, 2025). "Interestingly, it has been reported that treatment with vitamin D and its analog, eldecalcitol, reduced S1PR2 mRNA levels in murine circulating osteoclast precursors and alleviated ovariectomy-induced osteoporosis." (PMID 33922596, 2021). "The next important question is whether interfering with S1PR2 function using specific receptor antagonist(s) will demonstrate a therapeutic potential in the course of osteoporosis." (PMID 28524744, 2017). "Notably, in murine studies inhibiting S1PR2 by its specific inhibitor, JTE013, alleviated osteoporosis induced by RANKL and attenuated periodontal alveolar bone loss induced by oral bacterial inflammation." (PMID 33922596, 2021). "Moreover, wild type mice treated with a specific S1PR2 antagonist (JTE013) changed monocyte migration behavior induced by RANKL by enhancing monocyte percentage in the blood and alleviated osteoporosis induced by RANKL." (PMID 30609675, 2019). "Nevertheless, the utility of S1PR2 inhibition for the treatment of osteoporosis will depend not only on its effect on osteoclasts but also on that of osteoblasts." (PMID 28524744, 2017).
steatosis (6 papers, 2018 to 2024). Increased lipid within the cytoplasm of cells. "The inhibition or knockout of S1PR2 resulted in reduced fibrosis and angiogenesis, whereas steatosis and hepatocellular damage were comparable to those in wild-type mice after CDD feeding." (PMID 38753743, 2024). "S1PR2 signaling has been demonstrated to drive NASH, while genetic S1PR3 ablation predisposes HFD-fed mice to inflammation/steatosis." (PMID 36719377, 2023). "Further, the pictures of tissue biopsies also showed that steatosis was not affected by S1PR2/3 blockade in MCDHF-diet-treated livers (inset)." (PMID 31546702, 2019).
anaphylaxis (5 papers, 2016 to 2025). An acute hypersensitivity reaction that occurs from exposure to an allergen. "S1PR2 knockout mice or wild-type mice treated with the S1PR2 antagonist JTE013 show dramatically reduced signs of IgE-mediated anaphylaxis (drop in temperature, histamine release, and lung edema)." (PMID 36674974, 2023). "The role of S1PR2 has been investigated in mast cell-dependent passive systemic anaphylaxis and found that pharmacological or genetic silencing of S1PR2 reduced the antigen-induced lung perivascular edema and anaphylactic responses." (PMID 28352271, 2017).
chronic myeloid leukemia (5 papers, 2016 to 2025). "In addition, the SK1/S1P/S1PR2 signaling pathway leads to imatinib resistance in chronic myeloid leukemia (CML), and the SK2/S1P/S1PR1/S1PR3 signaling pathway renders the A549 lung cancer cell line resistant to etoposide." (PMID 40069781, 2025).
colorectal cancer (5 papers, 2020 to 2025). A primary or metastatic malignant neoplasm that affects the colon or rectum. "Previous investigations revealed that S1pr2 acted as a tumor suppressor in colorectal cancer." (PMID 35836816, 2022).
esophageal adenocarcinoma (5 papers, 2021 to 2025). A malignant tumor with glandular differentiation arising predominantly from Barrett mucosa in the lower third of the esophagus. "CBA can promote the aggressive development of esophageal adenocarcinoma cells and cancer stem cell proliferation by regulating S1PR2 levels." (PMID 36631680, 2023).
multiple sclerosis (5 papers, 2015 to 2025). A progressive autoimmune disorder affecting the central nervous system resulting in demyelination. "S1PR2 activity impairs remyelination, enhances BBB leakage, and demyelination in animal models of multiple sclerosis." (PMID 38916732, 2024).
allergic asthma (4 papers, 2020 to 2025). A asthma with a basis in a pathological type I hypersensitivity reaction. "S1PR2 is known to contribute to the pathogenesis of allergic asthma by inhibiting autophagy." (PMID 40005151, 2025).
gastric cancer (4 papers, 2016 to 2025). A primary or metastatic malignant neoplasm involving the stomach. "When S1P bound to and activated S1PR2, the migration of gastric cancer cells (AZ-521, exclusively expressed S1P2) was blunted." (PMID 34831211, 2021).
Hyperammonemia (4 papers, 2022 to 2026). An increased concentration of ammonia in the blood. "Hyperammonemia increases S1PR2 activation in the hippocampus by increasing the level of S1P and membrane expression of S1PR2." (PMID 38139078, 2023). "Hyperammonemia increased the phosphorylation of Src at Y418, which was reversed by blocking S1PR2 with JTE-013 or IL-1R with an endogenous antagonist." (PMID 38139078, 2023). "Hyperammonemia increased the IL-1β content in the hippocampus (139 ± 26%, p < 0.01), while blocking S1PR2 with JTE-013 completely reversed the increase in IL-1β (102 ± 17%; p < 0.05)." (PMID 38139078, 2023). "This supports that S1PR2 is a new therapeutic target to restore cognitive function in hyperammonemia and in patients with hepatic encephalopathy." (PMID 38139078, 2023). "To assess if this hypothesis is correct, we analyzed the effects of hyperammonemia and of blocking S1PR2 or IL-1R on the phosphorylation of Src and CCL2 contents." (PMID 38139078, 2023). "Chronic hyperammonemia enhances TNFR1 and S1PR2 activation in the cerebellum by increasing its membrane expression." (PMID 38671534, 2024). "Hyperammonemia also increased the CCL2 content in the hippocampus, which was also reversed by blocking S1PR2 or IL-1R." (PMID 38139078, 2023). "Hyperammonemia also increased the BDNF content in the hippocampus as analyzed using Western blot, and this increase was reversed by blocking S1PR2 or IL-1R or by inhibiting Src." (PMID 38139078, 2023). "We assessed if hyperammonemia increases the phosphorylation of p38 and the content of BDNF and if these effects are mediated by the S1PR2 → IL-1β → IL-1R → Src pathway." (PMID 38139078, 2023). "Hyperammonemia increased the phosphorylation of p38 MAP kinase at T180/182, which was reversed by blocking S1PR2 or IL-1R or by inhibiting Src with PP2." (PMID 38139078, 2023). "Hyperammonemia increased the content of the GABA γ2, α2, and β3 subunits, which were completely reversed by blocking TrkB with ANA12, TNFR1 with R7050, S1PR2 with JTE-013, or CCR2 with RS504393." (PMID 36233065, 2022). "Hyperammonemia increased the content of gephyrin and the phosphorylation of the β3 subunit of GABAA receptor in the cerebellum; these increases were reversed by blocking TrkB with ANA12, TNFR1 with R7050, S1PR2 with JTE-013, or CCR2 with RS504393." (PMID 36233065, 2022). "We show here that the hyperammonemia-induced changes in GAD65 and GAD67, and in the membrane expression of GAT3, and of the γ2, α2, and β3 subunits of GABAA receptors are also reversed by blocking TNFR1 signaling, S1PR2, or CCR2." (PMID 36233065, 2022). "However, the EV from control monocytes treated with forskolin (C-M-EV+Forsk) induced most of the changes in these pathways induced by hyperammonemia, except for the changes in membrane expression of TNFR1, S1PR2, and GluA1 and the increase in IL-1 receptor and CCL2." (PMID 41601700, 2026).
Hyperglycemia (4 papers, 2017 to 2025). An increased concentration of glucose in the blood. "A series of biological activities of endothelial cells mediated by S1PRs can be regulated by S1P, of which S1PR1 and S1PR2 play a key role in hyperglycemia-induced endothelial cell dysfunction." (PMID 36229882, 2022). "We had previously observed that S1PR2 displays a positive regulation of human umbilical vein endothelial cell dysfunctions induced by hyperglycemia." (PMID 30999892, 2019). "RhoA/ROCK1 is the key signaling pathway that couples S1PR2 and modulates endothelial cell dysfunction induced by hyperglycemia." (PMID 30999892, 2019). "Collectively, these data indicate that S1PR2 is critical in the remodeling of mitochondrial morphology and mitochondrial functions, and may participate in hyperglycemia-induced dysfunction of HRGECs, possibly by regulating RhoA/ROCK1." (PMID 30999892, 2019). "S1PR1 and S1PR2 were found to be involved in endothelial vascular dysfunction under high-glucose conditions, where S1PR1 protein and mRNA levels decreased during hyperglycemia, and S1PR2 levels increased." (PMID 41301404, 2025). "Therefore, S1P can mediate hyperglycemia-induced dysfunction of HUVECs through binding to S1PR1 and S1PR2." (PMID 36229882, 2022).